CD4 (CD4 molecule)
Diseases named in the same sentence as CD4 in open-access papers (continued):
Sharing a sentence is not in itself a finding about the gene and the disease.
infection (continued). "In this study, we have analyzed the expression and function of CD39 on conventional mouse and human CD4+ and CD8+ T cells following activation and during infection of wildtype and CD39-deficient mice with Listeria monocytogenes (Lm)." (PMID 29742141, 2018). "This was confirmed by the adoptive transfer of the lung CD4+ T cells from convalescent mice to naïve, sub-lethally irradiated mice, which significantly reduced the bacterial burden after infection of these mice with B. pertussis." (PMID 30692990, 2018). "Differentiation of naive CD4+ T-cells into functionally distinct T helper (Th) subsets is critical to immunity against pathogen infection." (PMID 29311549, 2018). "We evaluated the effect of PH-797804 treatment on percentages of total CD4+ T cells and CM CD4+ T cells, which is considered an earlier prognostic marker in the infection, as CM CD4+ T cells decline earlier than total CD4+ T cells." (PMID 30161247, 2018). "Both sequential and simultaneous infection with these viruses resulted in significant and permanent expansion of CD4 and CD8 TEM, to levels consistent with those seen in humans, as well as an increase in KLRG1 expression." (PMID 29963060, 2018). "The frequencies measured in the QVOA are in the range of 0.1–10 infections units per million (IUPM) resting CD4+ T cells." (PMID 29433524, 2018). "The inhibitory cell receptor NKG2A on NK cells was correlated with VL, CD4 count, and outcome post-infection in the in HLA section." (PMID 30534128, 2018). "There was no significant distinction in spite of a progressive decrease in the number of CD4+CD25+FoxP3+ Tregs 2 weeks after infection with L3 among the mice treated with PAS-5 (P > 0.05), while it was increased at 3 weeks compared with those of the control." (PMID 29843794, 2018). "The integrins α4β1 and α4β7 are involved in the migration of effector CD4+ T cells to this site as blockade of integrin α4 blocks uterine T cell homing during the early phase of infection." (PMID 29904388, 2018). "For the evaluation of the effect of potential factors on the model, accuracy was calculated in subjects with different gender, age, treatment, CD4+ T cell counts, and infection routes." (PMID 29568753, 2018). "CD4 TRM cells localized within barrier tissues are poised to provide immediate protection from re-challenge infection." (PMID 30386342, 2018). "Infection with human immunodeficiency virus-type 1 (HIV-1) results in CD4+ T cell destruction and progressive debilitation of the immune system." (PMID 29670623, 2018). "In splenocytes from BALB/c mice infected with B. pseudomallei MSHR5855 there was an early (3–7 days post-infection) increase in both CD4+ and CD8+ T cells (P < 0.001-P < 0.0001) as well as in monocyte/macrophages, NK cells, and granulocytes." (PMID 30500862, 2018). "In vivo data shows that Ag85b-specific CD4+ T cells can recognize Mtb-infected cells early during infection; however, recognition decreases after infection is established." (PMID 29782535, 2018). "By day 12 of coculture, MΦ-mediated trans infection of CD4+ T cells was significantly greater (P < 0.05) than virus production in cis-infected CD4+ T cells." (PMID 29643243, 2018). "Given the protective effect of CD4+ T cells in the primary infection and in the adoptive transfer protocol, we reasoned that these cells coordinate the protective immune response against ZIKV." (PMID 30087337, 2018). "Similar results were observed at 60 h post-infection, when both WT and Ezh2–/– Smarta CD4+ T cells were in 4th and 5th divisions." (PMID 30575739, 2018). "The recruitment of CD4+ T cells and other infection-permissive cells increases the number of target cells and can enhance HIV infection at the mucosa." (PMID 30648120, 2018). "Data by our lab and others suggest that FIV provirus and infected CD4+ T cells are epigenetically modulated during infection and that epigenetic modulators can be used to reverse these events." (PMID 29710792, 2018).
infection (continued). "The moDCs cocultured with CD4+ T cells at ratios of 1:1 and 1:8 efficiently amplifed infection by 2.6-fold, which resulted in TFV and RAL insensitivity to moDC-to-CD4+ T cell transmission." (PMID 29293546, 2018). "In our study, all HIV-infected women were followed for a range of 3–9 years from acute/early infection to the same endpoint, the initiation of cART when CD4 cell counts dropped below 200/mm3 on two consecutive visits." (PMID 29346424, 2018). "Cell-cell contacts are a prerequisite for efficient infection of CD4+ T-cells, while DC can be infected cell-free with viral biofilms." (PMID 29563906, 2018). "Cross-validation and simulation analyses indicate that the models developed provide more accurate information regarding the timing of infection than does CD4 count-based estimation, and they also provide useful population-level information." (PMID 29945571, 2018). "In a primary infection, CD4 and CD8 effectors are the most important for clearing virus, with Ab arising later." (PMID 29632538, 2018). "In contrast, levels of IL-12p70 are significantly lower in a secondary infection, indicating that CD4+ memory T cell-dependent induction of elevated IFNγ is likely IL-12-independent." (PMID 29438281, 2018). "During murine CMV (MCMV) infection, CD4+ Tcells maintain inflationary virus-specific CD8+ T-cell responses via IL-2 but not IL-21." (PMID 30279090, 2018). "Conversely, trans-infection involving LPS-matured DC leads to filopodial extensions of the CD4+ T-cells into the structured pocket of DC." (PMID 29415518, 2018). "Even in early phase of HIV infection, the dysfunction of HIV-specific T cells was observed in a group of patients (“rapid progressors”) who experienced a sharp decline of CD4+T cells after a short period of infection." (PMID 30564243, 2018). "The accuracies of these factors were not significantly different among groups with different gender, age, treatment, CD4+ T cell counts, and infection route." (PMID 29568753, 2018). "In contrast, nevirapine inhibited HIV RNA detection in cervical CD4 T cells by more than a log, suggesting that most of the viral RNA detected in T cells was the result of productive infection." (PMID 30532754, 2018). "Although patients enrolled in our study were in the early stage of HIV infection (110 ± 27 days post infection), they had quite different levels of CD4+T cells and viral loads when plasma sST2 was detected." (PMID 30564243, 2018). "While there was no discernible impact of maternal immunization on late infant oral virus acquisition, we observed a strong correlation between the percentage of activated CD4+ T cells in infant peripheral blood and a reduced number of challenges to infection." (PMID 29359183, 2018). "First, CD4+ memory T cells are highly sensitive to low antigen concentrations, allowing them to respond rapidly upon secondary infection." (PMID 29438281, 2018). "TCM cells are a population with the capacity to produce high levels of IL-2, and this population was generated by skin immunization with iC+CT, while the infection mainly generated CD4+ T cells with an effector phenotype." (PMID 29946313, 2018). "We were able to confirm that LEC stimulation rendered resting CD4+ T cells much more prone to infection than these T cells alone." (PMID 30285810, 2018). "We were also interested to see if CD4 T cells, the primary producers of IL-10 in this infection, were also found localized with fibrin(ogen) in the vessels." (PMID 29866139, 2018). "Immunized mice also induced higher levels of CD4+ IL-17A+ T cells by our final time point of 22 weeks post infection, similar to findings in human clinical studies." (PMID 29795025, 2018). "Then, we assessed the percentile of IFN-γ or TNF-α producing CD4 or CD8 T cells by flow cytometry at 4 days after initial infection." (PMID 30233599, 2018). "A multi-specific, robust, continuous, CD4+ -T-cell-specific Th1 response during HCV infection results in the clearance of infection." (PMID 29891859, 2018).
infection (continued). "Host cell infection starts with the involvement of the gp120 subunit of the viral envelope (Env) glycoprotein-network through CD4." (PMID 30416610, 2018). "LTNPs are defined by the maintenance of normal CD4+T cells counts for more than 8 years after infection." (PMID 30687333, 2018). "Replication of HTLV-1 occurs either by infection of new cells, or by mitotic division and clonal proliferation of infected CD4+ T-cells." (PMID 29563906, 2018). "Once the virus accesses tissue resident CD4+T cells, its primary targets, integration of the viral genome into the host genome establishes lifelong infection." (PMID 30648120, 2018). "By contrast, relatively few CD4+ T cells are recruited to the tracheal mucosa (as compared to the LRT) during the acute phase of infection." (PMID 29904388, 2018). "Surprisingly, expression of PD1 was largely unchanged, and no long-term difference in expression of CTLA4 was observed on antigen-experienced CD4 or CD8 cells in mice that received all three infections compared with mice that received mock infections." (PMID 29963060, 2018). "CD4+ T cells perform important roles in adaptive immune responses and limit intracellular pathogens in the early stage of infection, while CD8+ T cells participate in the resistance in the later stage of intracellular infection through cytolytic activity." (PMID 30564214, 2018). "Overall, depending on the median, 25% or 75% estimates of CD4 count at the time of infection 53.2% of HIV-infected patients (25% 75% estimates 43.7% and 64.4%, respectively) acquired HIV after having arrived in French Guiana." (PMID 29420591, 2018). "Age, sex, risk factors, HIV diagnosis time, time on ART, time on previous triple therapy, nadir CD4 count and infection by HCV were similar in the three groups of patients." (PMID 30362663, 2018). "CagY is an ortholog of VirB10 that, unlike other VirB10 orthologs, has a large middle repeat region (MRR) with extensive repetitive sequence motifs, which undergo CD4+ T cell-dependent recombination during infection of mice." (PMID 29764950, 2018). "They showed infection inhibition in primary human CD4+ T cells supporting these factors as key genes in HIV infection with loss-of-function variants without impairing cell viability." (PMID 30728828, 2018). "This reduction correlated with previous observations of reduced syncytia in cells transiently expressing Env and neutralization of HIV-1HXB2 infection of HeLa cells expressing CD4." (PMID 30359435, 2018). "Following infection with herpes simplex virus or contact sensitization to induce local inflammation, IFNγ producing CD4 T cells increased in the skin and clustered around hair follicles in association with CCL5 producing CD11b and CD8 T cells." (PMID 30386342, 2018). "Single factor analysis revealed that risk factors for complicated infection in patients with AAV included age, smoking, pulmonary involvement, hemoglobulin, albumin, SCr level, CD4 + T cell count, BVAS, and immunosuppressive therapy with MMF, CYC and TW." (PMID 29902982, 2018). "SIV studies in macaques suggest that CCR6+ CD4+ Th17 cells are preferential targets for early infection in the vaginal mucosa, possibly due to high levels of CCR5 expression." (PMID 29346424, 2018). "We have recently reported that infection with Bordetella pertussis induces CD69+ CD4 TRM cells and a significant proportion of these cells stably express CD103 through the course of infection and after clearance of the bacteria." (PMID 30147701, 2018). "HIV-specific CD4 T cell responses have been linked with neutralization breadth and elevated GC activity in bnAb inducers has been indicated by increased frequency of circulating memory T follicular helper (TFH) CD4+ cells, particularly early in infection." (PMID 30055627, 2018). "Genetic deletion of Uba3 in T cells resulted in a slight reduction of CD4+ T cells in the spleen, and more notably, the difference was exaggerated after P. yoelii 17XNL infection." (PMID 30462731, 2018).
infection (continued). "Having identified the expression of GLUT1, 3, 4, and 6 in activated human CD4+ T cells, we next turned our attention to their expression after the infection with HIV-1." (PMID 29518929, 2018). "The protective effect was dependent upon the presence of CD4+ T cells, as mice treated with CD4-depleting antibody prior to infection had bacterial loads similar to a primary infection." (PMID 29438281, 2018). "Follow-up studies have further characterized the phenotype of these cells containing integrated HIV DNA, as well as shown the correlation between the integration levels and clinical parameters, such as duration of infection, CD4 count and viral load." (PMID 29452580, 2018). "To study the distribution of CD4+ memory T cell subsets in Ss infection, we examined the counts of four different CD4+ T cell subsets (naive, central memory, effector memory and effector) in INF and UN individuals at baseline." (PMID 29795573, 2018). "CD4+ T cells counts in blood were restored to near pre-infection levels, and gut CD4+ T cells also recovered." (PMID 29478152, 2018). "We saw a dose-dependent relationship between effector-to-target cell ratio and suppression of HIV-1 replication, indicating that the CD8+ T cells are directly responsible for suppressing infection in autologous CD4+ T cells." (PMID 29466365, 2018). "Given the essential role of CD4+ T on survival, the impact of CD4+ T cell depletion on the generation of ZIKV neutralizing antibodies upon PE243 infection was determined through in vivo and in vitro heterologous neutralization assays." (PMID 30087337, 2018). "By day 8 p.i. the majority of the TCR-βhiNK1.1+CD4+ T cells exhibited a CD44hiCD62Llo phenotype indicative of activated effector T cells and maintained this phenotype over the course of infection." (PMID 30374346, 2018). "Go 6976 and GSK 2334470 also reduced infection of CD4+ T cells by HIV as measured by EGFP accumulation." (PMID 29970186, 2018). "Conversely, we have good reason to believe that uptake of apoptotic HIV-infected lymphocytes by macrophages can provide a route to infection of healthy CD4+ T cells." (PMID 29441073, 2018). "Following infection, polyclonal CD4+ T cells suppressed Mtb growth more efficiently in MHC class II-expressing cells than in MHC class II-deficient cells." (PMID 29782535, 2018). "In contrast, the infection induces a potent immune response in mice’s skin mediated by CD4+ T cells with an effector phenotype that produces high levels of IFN-γ and TNFα." (PMID 29946313, 2018). "Diminished CD200–CD200R signaling in LdCen−/− infection enabled proliferation of CD4+ T cells and resulted in the induction of pro-inflammatory cytokines and suppression of anti-inflammatory response." (PMID 29915577, 2018). "Based on this observation, we proposed that α4β7high memory CD4+ T cells are early targets of infection following mucosal transmission." (PMID 29478152, 2018). "We noted an increase in CD8+ T cells (P < 0.0001) early (3–7 days, post-infection) after infection with B. pseudomallei 1106a, and we saw a significant increase in CD4+ T cells (P < 0.0001) later (21 to 28 days post-infection) after infection." (PMID 30500862, 2018). "In the initial phase of infection, CD4+ T lymphocytes participate in the reduction of parasite density." (PMID 30126413, 2018). "Primary CD4+ T cells were activated with αCD3/CD28 beads + 20 U/mL IL-2 for 3 days before infection with different amounts of HIVGKO (input, ng/p24) and analyzed by flow cytometry 4 days post-infection." (PMID 29714165, 2018). "On day 8 post-infection (8 dpi), both wild-type and Ezh2–/– CD4+ T cells were activated at similar frequency, but fewer activated CD4+ T cells were detected in Ezh2–/– mice." (PMID 30575739, 2018). "Recently, Sivro and colleagues reported that, in HIV-infected women, α4β7high memory CD4+ T cells are preferentially depleted from gut tissues as early as the first 2 weeks following infection." (PMID 29478152, 2018).
infection (continued). "CD4 cell is very much important in enhancing the immune system in fighting infection via the adaptive immune system." (PMID 30344800, 2018). "Cellular cholesterol is essential for HIV-1 trans infection of CD4+ T cells mediated by DC and B cells." (PMID 29643243, 2018). "The reports of “drug ineffective” (in this case, failure of the vaccine to protect against infection) among HIV-positive persons with CD4 <500 cells/mm3 reflect the immunocompromised status of these persons." (PMID 29920551, 2018). "EC2 elicited a weaker CD8+ Gag response at 1 year post-infection, that declined over the follow-up period, and low magnitude CD4+ T-cell responses to Gag and Pol were detected at 1 and 5 years post-infection." (PMID 29370775, 2018). "The frequency of IL-17-secreting, PPD-stimulated CD4+ T cells from lungs from stat3fl/fllysm cre mice 4 and 8 weeks after infection with M. tuberculosis were elevated when compared to stat3fl/fl controls." (PMID 29338039, 2018). "The CD4:CD8 T cell ratio was reduced on average by 30% 20 h post-infection and by 70% by Day 5 post-infection." (PMID 30532754, 2018). "Adoptive transfer of the CD4 T cells that develop in PMIF-immunized mice during Plasmodium blood-stage infection also conferred full protection to blood-stage infection in naïve hosts." (PMID 30006528, 2018). "As expected, CD4+ T cells from all SN, including SN4 and SN5, were susceptible to cis infection with a high concentration of HIV-1 (MOI, 10−1)." (PMID 29643243, 2018). "Infection results in the percentage of CD4+CD25+Foxp3+ cells falling from 96.7% of all CD4+CD25+ cells in the CSF of EAE mice to 93.8%, and from 71.1% of all CD4+CD25hi cells in the CSF of EAE mice to 61.4%." (PMID 28975357, 2018). "We noticed that infection by the dual tropic HIV-1 89.6 in U87.CD4.CCR5 cells was almost equivalently inhibited by IFITM1 and IFITM2; however, IFITM3 still exhibited the strongest inhibition among all three IFITMs." (PMID 30087232, 2018). "Does a model with a drug-limited compartment hosting new short-lived CD4 cell infections have the capacity to predict viral load decay following treatment initiation?" (PMID 30016329, 2018). "While antibody and CD4+ T-cell responses are the primary effector mechanisms of protective immunity against blood-stage infection with Plasmodium parasites, several studies indicate that γδ T cells also participate in the immune response." (PMID 30619302, 2018). "We chose to load MΦ with an MOI of 10−3 because it is suboptimal for efficient cis infection of CD4+ T cells yet is highly effective in APC-T cell trans infection." (PMID 29643243, 2018). "As infection progresses in mice, Chlamydia disseminates to epithelial surfaces lining the uterine horns and oviducts, which become infiltrated by CD4+ and CD8+ T-cells, plasma cells, and macrophages." (PMID 29624589, 2018). "While memory B cell dysfunction is known to arise with HIV pathogenesis, all participants described here were superinfected within the first year of infection and had relatively high CD4 counts (>450 cells/μL) at the time of superinfection." (PMID 30269971, 2018). "Using a biomarker circumvents the need for sexual behavioural and migration data as identifying incident infection is based on testing specimens in real time in conjunction with routinely collected clinical data such as viral load and CD4 cell counts." (PMID 29924799, 2018). "The depletion of iNKT cells is reported to be because of either direct infection by HIV as they expressed both CD4 and CCR5 or due to Fas-mediated activation induced cell death." (PMID 29881390, 2018). "All these results suggest that, in T. cruzi acute infection, CD95/CD95L interaction leads to the apoptosis of immune cells, such as CD4+ T lymphocytes, which cannot control parasite multiplication and, therefore, contribute to the persistence of the infection." (PMID 30405039, 2018).